KRIT1 (KRIT1 ankyrin repeat containing)
Diseases named in the same sentence as KRIT1 in open-access papers (continued):
Sharing a sentence is not in itself a finding about the gene and the disease.
atherosclerosis (5 papers, 2019 to 2025). A disease characterized by the build-up of fatty material and calcium deposition in the arterial wall resulting in partial or complete occlusion of the arterial lumen. "Accordingly, our previous study demonstrated that KRIT1 heterozygous mice are susceptible to the development of metabolic-related comorbidities associated with chronic oxy-inflammatory conditions, such as atherosclerosis." (PMID 36232456, 2022). "In an attempt to determine the molecular mechanisms underlying KRIT1 deficiency-induced ED, we investigated the Notch signaling pathway, which is becoming increasingly recognized as a major player in preventing vascular ED and, thus, atherosclerosis." (PMID 31590384, 2019). "This background prompted us to investigate whether KRIT1 loss-of-function causes ED in the arteries and may predispose to the onset and progression of atherosclerosis in the presence of concomitant risk factors, such as inflammation or dyslipidemia." (PMID 31590384, 2019). "Overall, our findings point to the novel concepts that KRIT1 deficiency in ECs causes a redox-dependent downregulation of Notch1 activation and upregulation of proinflammatory endothelial CAMs, leading to a consequent increased susceptibility to ED and atherosclerosis." (PMID 31590384, 2019). "The aim of this study was to address whether KRIT1 loss-of-function predisposes to the development of pathological conditions associated with enhanced endothelial cell susceptibility to oxidative stress and inflammation, such as arterial endothelial dysfunction (ED) and atherosclerosis." (PMID 31590384, 2019). "Taken together, these data suggest that KRIT1+/− mice have a significantly increased susceptibility to fatty streaks deposition and VCAM-1 mRNA expression in atherosclerosis-prone regions of the aorta under stressful conditions, such as a chronic consumption of HF diets." (PMID 31590384, 2019). "Furthermore, there is evidence that KRIT1 silencing impacts Delta-Notch and RhoA/ROCK signaling pathways, which are clearly implicated in ED and atherosclerosis." (PMID 31590384, 2019). "Consistent with a potential role for KRIT1 in genetic susceptibility to atherosclerosis, two recent genome-wide association studies (GWAS) have implicated another CCM gene, CCM2, in coronary artery disease (CAD), a condition that is usually caused by atherosclerosis." (PMID 31590384, 2019).
breast carcinoma (5 papers, 2021 to 2025). "Finally, a recent study reports that expression of Krit1, Ccm2, and Pdcd10 are reduced in metastatic breast cancer tissues compared with the primary tumor, which indicates that CCM proteins might participate in tumorigenesis and metastasis." (PMID 38980708, 2024).
vascular malformation (5 papers, 2016 to 2025). A non-neoplastic disorder that is the result of defects of vascular morphogenesis. "Cutaneous vascular malformations have been reported in 9% of patients with familial CCM, mainly associated with KRIT1 gene variants." (PMID 33651268, 2021).
colorectal cancer (4 papers, 2022 to 2025). A primary or metastatic malignant neoplasm that affects the colon or rectum. "Exosomal miR-21-5p secreted by colorectal cancer cells activates the β-catenin signaling pathway in ECs by targeting Krev interaction trapped 1 (KRIT1), which enhances angiogenesis and vascular permeability in colorectal cancer (CRC)." (PMID 40002766, 2025). "Delivery of miR-21-5p from colorectal cancer cells to ECs by exosomes promotes angiogenesis and vascular permeability in colorectal cancer via targeting Krev interacting capture protein 1 (KRIT1) on recipient ECs." (PMID 36358833, 2022). "As for the mechanism of miR-21 mediates VEGF expression and angiogenesis, recent studies have shown that miR-21 increases VEGF expression via ERK and AKT signal in vascular endothelial cells; miR-21 promotes angiogenesis by targeting SPRY2 and/or KRIT1 in osteoarthritis and colorectal cancer." (PMID 35586052, 2022).
diabetes (2 papers, 2022). "Intriguingly, the accumulation of AGEs and the imbalance between pro- and anti-inflammatory AGE receptors observed in the liver of KRIT1+/− mice were typical aspects already described in diabetes and obesity, and indicate the possible activation of a low-grade chronic inflammatory response." (PMID 36232456, 2022).
bowel dysfunction (1 paper, 2024). Any disease in which the causes of the disease is a perturbation of the lower digestive tract leading to its dysfunction. "We report a case of a patient with a KRIT1 mutation presenting with dysautonomia causing urological, sexual, and bowel dysfunction." (PMID 38425333, 2024).
glioblastoma (1 paper, 2015). The most malignant astrocytic tumor (WHO grade IV). "The consequences of KRIT1 amplification are not completely clear, but we may hypothesize that it is required for proper angiogenesis development, which is a hallmark of glioblastoma, and that it may also help decrease apoptosis." (PMID 25679508, 2015). "Interestingly, among those genes we find the well-known glioblastoma oncogene EGFR and tumor suppressors CDKN2A and PTEN, but also novel candidates such as KRIT1 and PAOX described in the previous paragraph." (PMID 25679508, 2015).
of glass (1 paper, 2018). "Within this complex, KRIT1 (also known as CCM1) and the transmembrane protein HEG1 (also known as Heart of glass) physically interact with each other." (PMID 29364115, 2018).
schwannoma (1 paper, 2025). A benign, usually encapsulated slow growing tumor composed of Schwann cells. "Proposed pathways of tumorigenesis include loss of Merlin-mediated inhibition of the MAP kinase MEK/ERK cascade, abnormalities in the PI3K/mTOR pathway, interactions between vascular endothelial growth factor (VEGF) secreted by schwannoma cells and endothelial cells, and KRIT1 gene mutations." (PMID 40342451, 2025).
tuberous sclerosis complex (1 paper, 2023). "For example, diagnoses of tuberous sclerosis complex and multiple cavernoma (due to KRIT1), can often be made based on neuroimaging and clinical criteria; genetic testing is primarily performed to confirm diagnosis, inform surveillance for co-morbidities, and allow for family counselling." (PMID 37264783, 2023).
tumor (17 papers, 2007 to 2026). "The reduction in H2O2 caused by MG-H1 depletion appears to disrupt KRIT1-mediated signaling, potentially impairing its tumor-suppressive functions and thereby contributing to cancer progression." (PMID 41009024, 2025). "The loss of KRIT1 function, which triggers the tumor inhibitory effects of Krev-1-rap1a, would further boost Ras protooncogene effects." (PMID 34824953, 2021). "This study confirms our earlier hypothesis that KRIT1 functions as a tumor suppressor and uncovers a compelling link between its loss and enhanced cancer aggressiveness." (PMID 42074063, 2026). "In this context, the observed downregulation of H2O2 may interfere with KRIT1-mediated signaling, leading to a loss of its regulatory functions and contributing to tumor progression." (PMID 41009024, 2025). "This novel link expands the molecular framework through which oxidative stress influences PCa biology and highlights KRIT1 as a potential mediator of redox-dependent tumor control mechanisms." (PMID 41009024, 2025). "KRIT1 is also the target of miR-21, a microRNA over-expressed in many tumor types that displays oncogenic activity." (PMID 38980708, 2024). "It has been proposed that KRIT1 acts as a tumor suppressor multiple times over the past two decades." (PMID 38980708, 2024). "The target genes of miR-21 include PDCD4, SMAD7, PTEN, HIF-1α, KRIT1, and other tumor suppressor genes." (PMID 37316504, 2023). "Even though LPS treatment failed to diminish the expression of genes involved in proliferation and malignancy such as GEN1, KRIT1, CENPF, STYK1, and Sam68/KHDRBS3, it did reduce the expression of numerous genes implicated in tumor growth." (PMID 35884586, 2022). "In line with these previous reports, our findings reinforce the role of KRIT1 as a tumor suppressor (its reduced expression contributes to the enhanced growth of aggressive PCa cells), thereby adding a new layer of understanding to its involvement in cancer biology." (PMID 41009024, 2025). "In addition, it has been described that KRIT1 is an emerging crucial player in redox homeostasis and an increasingly recognized tumor suppressor in cancer biology." (PMID 41009024, 2025). "Additionally, the role of KRIT1 across different tumor types warrants further exploration, particularly in relation to its emerging function as a redox-regulated tumor suppressor." (PMID 41009024, 2025). "Krit1+/− ApcMin/+ mice also exhibited reduced survival due to increased tumor burden." (PMID 38980708, 2024). "Additionally, the association of Rap1A and Krit1 in cytoskeletal regulation and the presence of STAT1, linked to the urea cycle and tumor development, offered insights into Lucena 1’s distinctive biology." (PMID 39272999, 2024). "Despite this evidence, the labeling of KRIT1 as a tumor suppressor gene remains controversial." (PMID 38980708, 2024). "Also, Krit1 is a gene with a putative role in tumorigenesis, and miR-21 overexpression or silencing Krit1 mRNA levels increases tumor growth." (PMID 35572197, 2022). "Given the broader relevance of PI3K activation across multiple cancer types, KRIT1 may represent a context-specific biomarker or therapeutic target in a wide range of malignancies where glycation and redox imbalance converge to drive tumor progression." (PMID 41009024, 2025). "Additionally, investigating the role of KRIT1 in other cancer types and its interaction with oxidative stress pathways could provide further insights into its broader significance in tumor biology." (PMID 41009024, 2025). "Thus, as more and more evidence accumulates which supports the classification of KRIT1 as a tumor suppressor, we also continue to learn more about the role of KRIT1 in cancer biology, which may yield surprising insights into the function of these proteins in vascular biology, and beyond." (PMID 38980708, 2024).
tumor (continued). "Exosomal miR-21 in the tumor microenvironment had been widely known as a strong proangiogenic factor via targeting krev interaction trapped protein 1 (KRIT1) and PTEN, finally leading to tumor progression." (PMID 35757325, 2022). "A crucial NF-κB regulator, Sam68 (KHDRBS3), was also observed to be elevated in LPS-treated tumor enteroids, along with the genes GEN1, KRIT1, CENPF, and STYK1." (PMID 35884586, 2022). "Interestingly, while LPS treatment increased the proliferation and expression of the GEN1, KRIT1, CENPF, CPLANE1, STYK1, and KHDRBS3 genes, it decreased the expression of the cancer associated LOC610994, Gpatch4, SLC7A1, ATP13A2, and TEX45 genes in tumor enteroids." (PMID 35884586, 2022). "MiR-21 has been shown to affect cell proliferation, invasion, and the clinical outcome by downregulating the expression of tumor suppressors, such as PDCD4, TIMP3, RECK, and KRIT1." (PMID 28466015, 2017). "For instance, one study reported a negative correlation between miR-21-5p expression and KRIT1 levels in vessels adjacent to the tumor, suggesting a possible downregulation of KRIT1 within the tumor microenvironment." (PMID 41009024, 2025). "Importantly, our data uncover for the first time a functional link between this axis and the KRIT1 signaling pathway, indicating that the decrease in ROS levels downstream of MG-H1/RAGE desensitization acts as a critical modulator of intracellular signaling with potential tumor-suppressive roles." (PMID 41009024, 2025). "Some studies have found higher relative RNA expression levels of KRIT1 and CCM2 in cancer cell lines, as compared with normal primary cell lines, which would not be expected of a tumor suppressor." (PMID 38980708, 2024).
cancer (12 papers, 2021 to 2026). A tumor composed of atypical neoplastic, often pleomorphic cells that invade other tissues. "In this study, we investigated the role of KRIT1 in cancer cell migration and metastasis, with a focus on identifying novel interacting proteins and characterizing the intracellular signaling pathways activated upon its loss." (PMID 42074063, 2026). "This aspect will be investigated in future studies when we aim to better characterize the functional role of KRIT1 in prostate biology and cancer progression." (PMID 41009024, 2025). "Previous studies showed the pro-angiogenic properties of endogenous miR-21-5p and cancer cell derived-miR-21-5p to be dependent on KRIT1 and Spry1 in vessel endothelial cells." (PMID 35346324, 2022). "Cancer-derived exosomal miR-21-5p could induce angiogenesis and vascular permeability via the inhibition of KRIT1." (PMID 35549815, 2022). "In addition, some have pointed to a lack of association of KRIT1 with cancer in genome wide association studies." (PMID 38980708, 2024). "Despite its ubiquitous expression, limited research has explored KRIT1’s involvement in pathologies beyond CCM, including cancer." (PMID 41009024, 2025). "Future studies can explore new signaling paradigms involving KRIT1 and the CCM proteins that could be exploited to provide new therapies for CCM, other cardiovascular diseases, or even cancer." (PMID 38980708, 2024). "In this review, we have discussed the contribution of KRIT1 to blood vessel morphology, barrier regulation, immune cell function, cancer biology, and examined what is known about the role of KRIT1 in non-vascular cell types." (PMID 38980708, 2024). "Our results suggest the possible roles of GEN1, KRIT1, CENPF, STYK1, and Sam68/KHDRBS3 in promoting cancer cell proliferation, and these findings may provide a potential therapeutic target to control mast cell malignancy." (PMID 35884586, 2022). "In the present study, we focused on the roles of miR-21-5p and KRIT1 in cancer-adjacent vessels, but not cancer cells, which differed from previous studies." (PMID 34088891, 2021). "Recent evidence supports the hypotheses that KRIT1 regulates the function of both endothelial and non-endothelial cells and may play a role in cancer biology." (PMID 38980708, 2024). "Moreover, a negative relationship between miR-21-5p and KRIT1 expression levels was observed in cancer-adjacent vessels." (PMID 34088891, 2021). "However, there has been no published data about the roles of KRIT1 in cancer-adjacent vessels." (PMID 34088891, 2021).
genetic disorder (5 papers, 2016 to 2026). "As a human genetic disease, three genes have so far been identified, whose loss-of-function mutations cause CCM disease: KRIT1 (CCM1), CCM2, and CCM3 (PDCD10)." (PMID 36831015, 2023).
infection (2 papers, 2022 to 2024). The state of being infected such as from the introduction of a foreign agent such as serum, vaccine, antigenic substance or organism. "However, to limit potential overexpression artifacts in our functional assays, we lowered the adenoviral multiplicity of infection (MOI) so that our mCherry-KRIT1 constructs were expressed at roughly 1.5-fold endogenous KRIT1." (PMID 34918736, 2022).
bacterial infection (1 paper, 2026). "We find also that kri-1/KRIT1 is required for host tolerance to bacterial infection, fecundity, and normal development." (PMID 42239296, 2026).
neurodevelopmental disorder (1 paper, 2025). A behavioral and cognitive disorder with onset during the developmental period that involves impaired or aberrant development of intellectual, motor, or social functions. "We demonstrate that removing the target exon significantly increased protein translation (between 1.4-5.5 fold) in a luciferase reporter assay for four of six prioritised target 5’UTR exons in neurodevelopmental disorder genes (CTCF,GRIN2B,KRIT1, andTSC1)." (PMID 41573882, 2025).
vasculopathy (1 paper, 2023). "Specifically, all four patients with structural vasculopathy subtype had a monogenic etiology (4/4, 100%): KRIT1 for CCM, RNF213 for MD, ENG for HHT, and PKD1 for PKD." (PMID 36580209, 2023).
KRIT1 also shares sentences with these, for which no sentence is quoted: hemorrhagic stroke (4 papers); Stroke (3); angiomas (2); arteriovenous malformations (2); prostate carcinoma (2); aortic aneurysm (1); arthrogryposis (1); astrocytoma (1); breast tumors (1); capillary malformation (1); cardiovascular diseases (1); cerebral cavernous malformation 1 (1); cerebral malaria (1); coronary artery disease (1); developmental venous anomaly (1); dysautonomia (1); epilepsy (1); hemorrhage (1); hepatic angiomas (1); hepatic angiosarcoma (1); hepatic cancer (1); hereditary pulmonary arterial hypertension (1); Hyperglycemia (1); Hypertension (1); intestinal disease (1); intracranial hemorrhage (1); Leukoencephalopathy (1); liver disease (1); lung fibrosis (1); lymphatic malformation (1).
A further 11 diseases each share a sentence with KRIT1 in 1 paper.